LNCEGFL7OS (lncRNA EGFL7 opposite strand)
Synonyms: HSPC324
Gene: Long non-coding RNA gene on chromosome 9 (136,647,865 to 136,663,334, reverse strand). Ensembl gene ENSG00000228401.
Diseases named in the same sentence as LNCEGFL7OS in open-access papers:
LNCEGFL7OS is named in the same sentence as 2 diseases in open-access papers, as found by Europe PMC text mining. Sharing a sentence is not in itself a finding about the gene and the disease.
LNCEGFL7OS shares sentences with these, for which no sentence is quoted: cancer (1 paper); lung carcinoma (1).